GSK3B (glycogen synthase kinase 3 beta)
Diseases named in the same sentence as GSK3B in open-access papers (continued):
Sharing a sentence is not in itself a finding about the gene and the disease.
colon carcinoma (continued). "In conclusion, we show for the first time that galectin-3 silencing sensitizes MDR cells to epirubicin by inhibiting P-gp and MRPs and the activation of the mitochondrial apoptosis pathway through modulation of the β-catenin/GSK-3β pathway in human colon cancer cells." (PMID 24303084, 2013). "We found that DACT1 binds to axin and GSK-3β in colon cancer cells." (PMID 22470507, 2012). "The research found that the inhibition of SIRT4 would activate GLS, thereby initiating AKT activation, suggesting that GLS might influence the proliferation, migration, and invasion of colon cancer cells through the AKT/GSK3β/CyclinD1 pathway under the regulation of SIRT4." (PMID 41152153, 2025). "Moreover, lycopene exhibited promising in vitro anticancer activity against human colon cancer cells (HT-29) by inhibiting the phosphorylation of Akt, glycogen synthase kinase-3β (GSK-3β), and ERK 1/2 proteins and by suppressing MMP-7 expression, thus preventing metastasis and angiogenesis." (PMID 39478959, 2024). "Additionally, JSD could lead to an increase in expression of E-cadherin, and a decrease in expression of N-cadherin, Vimentin, p-AKT1, AKT1, p- GSK-3β, Snail, Slug, and Twist in colon cancer cells." (PMID 31772677, 2019). "In addition, GSK-3β/Bax axis is indispensable for using SC66 to treat colon cancer." (PMID 31168297, 2019). "Through two phosphodegron motifs found within CDX2, FBXW7 promotes CDX2 ubiquitination and degradation in a GSK3β-dependent manner, resulting in decreased CDX2 expression and activity in colon cancer cells." (PMID 41373479, 2025). "Our data study supports that PCCA significantly influences colon cancer progression and metastasis through the modulation of EMT and the ERK/GSK-3β signaling pathway." (PMID 39744168, 2025). "Collectively, our data indicate that PLE0 exerts an anti-metastatic effect in human colon cancer cells by inhibiting epithelial–mesenchymal transition and MMP-2/9 via downregulation of GSK3β/β-catenin and JNK signaling." (PMID 38732748, 2024). "CXCL5 can promote colon cancer metastasis by activating the ERK/Elk‐1/Snail and AKT/GSK3β/β‐catenin signaling pathways." (PMID 37666495, 2024). "TWS119 is a potent inhibitor of GSK‐3β and it has been reported that TWS119 increases the replication and cytolytic activity of human γδT cells against human colon cancer cells." (PMID 37859510, 2023). "After GSPT1 was silenced, the expression of GSK-3β, p21, and p27 increased, and the expression of CyclinD1, CDK4/6, cyclinE, and CDK2 decreased; these changes affected the progression of colon cancer cells from G1 phase to S phase and blocked the cell cycle." (PMID 33819920, 2021). "In this study, we identified a strong synergistic inhibitory effect of GSK3β inhibition and PARP inhibition on all tested colon cancer." (PMID 33589588, 2021). "This study also suggests that imbalance activation and inactivation phosphorylation of GSK3β lead to its impaired function and, as a consequence, enhance Hh-GLI signaling and survival of colon cancer cells." (PMID 34572373, 2021). "Furthermore, treating colon cancer cells (both cell lines and ex vivo specimens) with GSK3β inhibitor lithium chloride (LiCl) enhances its phosphorylation on S9 and promotes the formation of Gli3/SuFu/GSK3β complex, with consequent phosphorylation and inactivation of Gli3." (PMID 32767962, 2021). "This change in protein expression leads to a reverse in the EMT status of colon cancer cells, presumably through the AKT/GSK-3β signaling pathway." (PMID 31772677, 2019). "Our study found that the inhibition effects of JSD on colon cancer EMT and metastasis were weakened with knockdown of AKT1 and inactivation of AKT/GSK-3β signaling." (PMID 31772677, 2019). "Conversely, overexpression of AKT1 and activation of the AKT/GSK-3β signaling pathway enhanced JSD's ability to inhibit EMT and colon cancer metastasis." (PMID 31772677, 2019).
colon carcinoma (continued). "Together, these morphological and biochemical findings suggest that GSK3β participates in proper localization and function of the mitotic mediators dynein and TPR to sustain mitosis for colon cancer cell propagation." (PMID 29568361, 2018). "This study found that colon cancer cells exposed to DEHP or MEHP exhibited increased cell viability and increased levels of P-glycoprotein, CD133, Bcl-2, Akt, ERK, GSK3β, and β-catenin when treated with oxaliplatin or irinotecan, as compared to control." (PMID 29568348, 2018). "We previously demonstrated the therapeutic effect of GSK3β inhibitors (AR-A014418 and SB-216763) against SW480 and HT-29 colon cancer cell xenografts in athymic mice." (PMID 29568361, 2018). "In human colon cancer cells, IGF-I stimulates β-catenin relocation and stability through the inactivation of GSK-3β, which increases cell motility and contributes to colon cancer metastasis." (PMID 28137302, 2017). "In the present study, idelalisib induces PUMA expression through GSK-3β/NF-κB pathway following AKT inhibition and initiates apoptosis through the intrinsic apoptosis pathway in colon cancer cells." (PMID 28008149, 2017). "Mechanistically, we found that DDA1 promoted proliferation and invasion in colon cancer cells by enhancing and stabilizing p-IKKβ and triggering the phosphorylation and degradation of IκBα followed by the activation of NFκB/CSN2/GSK3β signaling." (PMID 26942699, 2016). "Complementary to these results, a study demonstrated that in colon cancer cells celecoxib inhibited the c-Met/AKT pathway, resulting in decreased phosphorylation and thus increased activity of GSK3β, leading to an increase in β-catenin phosphorylation." (PMID 27429001, 2016). "Taken together, our results indicate that Hes1 plays a quantitative role in the development and progression of colon cancer and suggest a mechanism that links Hes1 to Bmi-1/PTEN/Akt/GSK3β pathway." (PMID 26452029, 2015). "SMA significantly reduced the activities of PI3K/Akt, which corresponded with a decrease in GSK3β phosphorylation, an increase in β-catenin phosphorylation, and a reduction in nuclear β-catenin content in HT29 human colon cancer cells." (PMID 26544726, 2015). "Tissue samples taken from humans in the early stages of colon cancer—as the polyps progress towards becoming cancerous—had high levels of FAK, PYK2 and phosphorylated GSK3β." (PMID 26274564, 2015). "Treatment with GSK3β inhibitors, BIO or LiCl, under serum-starved conditions, induced the proliferations of colon cancer cells, CT26, HT29, and HCT116." (PMID 26544726, 2015). "GSK3B and SMAD3 are proteins involved in the KEGG colon cancer pathway and the remaining three are first-degree neighbors." (PMID 24886433, 2014). "The activation of Wnt signal, inhibition of APC/GSK3β/Axin complex, nuclear translocation of β-catenin, and up-regulation of Slug and Snail are key points of EMT regulation in colon cancer." (PMID 24039918, 2013). "In DLD-1 and LS174T colon cancer cells, activation of the EP2 receptor by PGE2 promotes the release of glycogen synthase kinase 3β (GSK-3β) from the adenomatous polyposis coli (APC)/Axin/β-catenin complex." (PMID 22126303, 2011). "Second, we identified 156 phospho-substrates specifically regulated by GSK3α, but not GSK3β, in vitro and in colon cancer cell lines." (PMID 37031867, 2023). "In this study, unexpectedly, we found that the expression of GSK3α, but not GSK3β, was significantly correlated with the overall survival of colon cancer patients in 4 independent cohorts." (PMID 37031867, 2023).
colon carcinoma (continued). "Based on our proteome and immunostaining data and publicly available proteome data from 4 independent colon cancer cohorts, we showed that GSK3α, but not GSK3β, was able to predict the prognosis of colon cancer patients." (PMID 37031867, 2023). "First, we demonstrated that high expression of GSK3α, but not GSK3β, was significantly correlated with unfavorable outcomes in colon cancer patients from four independent cohorts." (PMID 37031867, 2023). "Furthermore, EpEX enhances the epithelial-to-mesenchymal transition and metastatic potential of colon cancer cells by activating ERK and FAK-AKT signaling pathways, and it further stabilizes active β-catenin and Snail proteins by decreasing GSK3β activity." (PMID 37543570, 2023). "Therefore, we used EpAb2-6 to block the function of EpEX in colon cancer cells and analyzed the phosphorylation levels of HGFR, AKT, FAK, GSK3β, ERK, ADAM17, and presenilin 2 in HCT116 cells." (PMID 37543570, 2023). "In colon cancer, interleukin-1 (IL-1) and TAMs collaborate to activate NF-κB-dependent PDK1/AKT signalling in tumour cells, inactivating glycogen synthase kinase 3 beta (GSK3β), amplifying Wnt signalling, and fostering colon cancer cell proliferation." (PMID 38136392, 2023). "To decipher the roles of GSK3α in colon cancer, we profiled the in vitro and cellular phospho-substrates of GSK3α and identified 156 phosphosites specifically regulated by GSK3α but not GSK3β." (PMID 37031867, 2023). "Herein, we report that increasing the tetrahydrobiopterin:dihydrobiopterin ratio and recoupling nitric oxide synthase with sepiapterin in the colon cancer cell lines, HCT116 and HT29, inhibit their proliferation and enhance cell death, in part, by Akt/GSK-3β–mediated downregulation of β-catenin." (PMID 36998441, 2023). "The expression of GSK3β is higher in colon cancer cells and in colorectal cancer patients in comparison to normal counterparts." (PMID 36836894, 2023). "Yet, our research has revealed that GSK3α, rather than GSK3β, is significantly correlated with colon cancer patients' survival." (PMID 37031867, 2023). "ACP can significantly inhibit proliferation and induce apoptosis of colon cancer cells, which may be closely related to the regulation of PI3K/AKT/GSK3B signal transduction." (PMID 38102686, 2023). "Further investigations revealed that the inhibitory Ser9 phosphorylation of GSK3β was largely absent in colon cancer cell lines, whereas the activating Tyr216 phosphorylation remains, suggesting deregulated GSK3β function." (PMID 34572373, 2021). "Colon cancer liver metastasis has been connected with TRPM8 over-expression, and TRPM8 silencing decreased cell invasion and migration, possibly through the downregulation of p-AKT/AKT, p-GSK3β/GSK3β expression." (PMID 34445208, 2021). "For instance, highly active Akt does not fully inhibit GSK3β activity in pancreatic and colon cancer cells." (PMID 32767962, 2021). "Resveratrol is considered to be a promising anticancer drug for chemoprevention or therapy for colon cancer, targeting numerous cellular molecules, such as AKT serine/threonine kinase 1 (AKT1), AKT2, and AKT/GSK-3β/Snail signaling pathway, and increasing ROS production." (PMID 32244860, 2020). "Furthermore, TREM2 increases β-catenin phosphorylation by activating GSK-3β, which suppresses β-catenin accumulation and TCF4 transcriptional activity, resulting in the downregulation of tumorigenicity in colon cancer cells." (PMID 31489935, 2019). "In this study, we found that JSD could inhibit the migration and invasion of colon cancer cells, and could reverse the EMT status of colon cancer cells through the AKT/GSK-3β signaling pathway." (PMID 31772677, 2019).
colon carcinoma (continued). "Together, these data show that GSK-3β activates Bax directly and inhibits Bcl-xL simultaneously through the mitochondrial pathway, during which GSK-3β is necessary for the proapoptotic effect of SC66 in colon cancer cells." (PMID 31168297, 2019). "Moreover, a series of phosphorylation upregulation was observed along with downregulation of eIF3D in colon cancer cells, including AMPKα, Bad, PRAS409, SAPK/JNK, and GSK3β, as well as the cleavage of PARP." (PMID 31885740, 2019). "However, the discovery that JSD can reverse EMT and inhibit colon cancer invasion and metastasis through AKT/GSK-3B signaling is a novel finding." (PMID 31772677, 2019). "In summary, our study demonstrates that CDX2 inhibits the proliferation and tumor formation of colon cancer cells by suppressing Wnt signaling activity and reveals a molecular mechanism by which CDX2 regulates the transcriptional activation of GSK-3β and Axin2." (PMID 30631044, 2019). "For example, in contrast to the previous report that ILK increased transcription of the Snail gene in human colon carcinoma cells, the present study indicates that ILK promoted the upregulation of Snail via multiple pathways involving HIF-1α, YB-1, and GSK3β at different cellular levels." (PMID 25821081, 2015). "However, in comparison with normal epithelial CCD-18Co cells, all colon cancer cells and CRC tumor tissues exhibited less phosphorylated β-catenin proteins and more phosphorylated GSK3β proteins, indicative of activated Wnt/β-catenin signaling." (PMID 26060426, 2015). "eIF3D is essential for colon cancer cell growth, and knockdown of eIF3D resulted in a significant reduction in cell proliferation probably due to activation of AMPKα, Bad, PRAS40, SAPK/JNK and GSK3β, as well as cleavage of PARP." (PMID 25370813, 2014). "It was further demonstrated that GSK-3β inhibition or down-regulation leads to a decrease in NF-κB activity within glioma cell lines and that GSK-3β has a role in modulating cell proliferation in prostate and colon cancer." (PMID 23915189, 2013). "The activation of Akt can trigger many downstream signaling cascades, and in colon cancer PGE2 has been shown to activate Akt and the downstream pathway of GSK-3β and β-catenin resulting in an increased proliferation, whereas an increased survival was due to Akt activation of PPARδ." (PMID 22276108, 2012). "exhibited cytotoxicity against various human colon cancer cells and induced G0/G1 phase cell cycle arrest in HCT116 human colon cancer cells via downregulation of cyclin D1 through phosphorylation-dependent ERK1/2, p38 or GSK3β, and cyclin D1 transcriptional inhibition through Wnt signaling." (PMID 38966207, 2024). "Phosphorylation of GSK-3β at Ser9 and total β-catenin levels suggested that the suppression of EpCAM might be due to alterations in the TREM2-mediated Wnt/β-catenin signaling pathway and that TREM2 might be involved in the tumorigenicity of colon cancer." (PMID 31489935, 2019). "In the present study, phosphorylation of AMPKα, Bad, PRAS40, SAPK/JNK and GSK3β, as well as cleavage of PARP was elevated in eIF3D knockdown group, adding the evidence that depletion of eIF3D could suppress colon cancer cell growth via the induction of cell-cycle arrest and apoptosis." (PMID 25370813, 2014).
colon carcinoma (continued). "Finally, treatment of cells with LY29004 completely prevented the ability of IL-1β to protect colon cancer cells from TRAIL-induced apoptosis, implying that macrophages and IL-1β protect from TRAIL induced apoptosis through GSK3β dependent stabilization of Snail." (PMID 20661477, 2010). "Resveratrol was studied in vitro on AK4-knockdown colon cancer cells (SW480 and SW620) and showed that it could diminish the invasion and metastasis of colon cancer cells by reversing the expression of EMT (epithelial–mesenchymal transition) markers via the AKT/GSK-3β/Snail pathway." (PMID 36142147, 2022). "In summary, JSD may downregulate the EMT transcription factors Snail, Slug and Twist through the AKT/GSK-3β signaling pathway, leading to an upregulation of E-cad, and downregulation of N-cad and Vimentin, reversing EMT and inhibiting invasion and metastasis of colon cancer cells." (PMID 31772677, 2019).